IL18BP (interleukin 18 binding protein)
Diseases named in the same sentence as IL18BP in open-access papers (continued):
Sharing a sentence is not in itself a finding about the gene and the disease.
lung fibrosis (3 papers, 2021 to 2022). "All of these findings suggest that increased expression of IL-18BP is associated with progressive lung fibrosis, pulmonary dysfunction, and poor prognosis in IPF patients." (PMID 34086758, 2021). "Therefore, we hypothesized that the interleukin-18 binding protein can serve as a diagnostic and/or prognostic biomarker for idiopathic pulmonary fibrosis." (PMID 34086758, 2021). "In a mouse model of pulmonary fibrosis, the neutralization of the IL-18 receptor with IL-18BP abrogated bleomycin-induced pulmonary fibrosis." (PMID 35625564, 2022). "Recently, it was reported that administration of IL-18BP to a BLM-injury model improved lung fibrosis, but the trend of IL-18BP secreted in vivo is unclear." (PMID 34086758, 2021). "IL‐18BP inhibited IL‐18‐mediated epithelial wound repair consistent with effects of IL‐18BP inhibiting EMT changes in the murine lung fibrosis model following bleomycin‐induced injury." (PMID 34194747, 2021). "Serum interleukin-18 binding protein levels were significantly higher in idiopathic pulmonary fibrosis patients (5.06 ng/mL, interquartile range [IQR]: 4.20–6.35) than in healthy volunteers (3.31 ng/mL, IQR: 2.84–3.99) (p < 0.001)." (PMID 34086758, 2021). "Furthermore, BALF IL-18BP levels in the mouse models of subcutaneously injected bleomycin-induced lung fibrosis were positively correlated with lung hydroxyproline expression levels." (PMID 34086758, 2021). "First, IL-18BP itself is not the cause of the poor outcomes for IPF; although IL-18BP itself has anti-fibrotic and/or anti-inflammatory activity, its increased expression simply reflects increased expression of IL-18, which can promote lung fibrosis." (PMID 34086758, 2021).
malaria (3 papers, 2014 to 2019). Malaria is a serious and sometimes fatal disease caused by a parasite that commonly infects a certain type of mosquito which feeds on humans. "The elevated concentrations of sTNFR2, sICAM-1, and IL-18BP we observed in association with MiP in WLHIV, indicate a malaria-induced systemic inflammatory response." (PMID 31043691, 2019). "At Visit 1, compared with uninfected women, malaria-infected women had significantly higher levels of CHI3L1, CRP, sICAM-1, IL-18BP, sTNFRII, and sEng and lower levels of Leptin (p ≤ 0.005)." (PMID 31574087, 2019).
Stills Disease (3 papers, 2022 to 2024). "As expected, patients with rheumatologic hyperferritinemia (Stills Disease) had significantly higher total IL-18 (including free IL-18 and IL-18 in complex with IL-18BP) values, both per sample and maximum, compared to the infection and immune dysregulation subgroups." (PMID 39264477, 2024). "On a serum/plasma biomarker level Still’s disease is further hallmarked by elevated levels of bioactive, free IL-18 (not complexed by IL-18 binding protein (IL-18BP)); as well as S100 proteins, sCD163, IL-6, IL-8, IL-17, and TNF-α." (PMID 38231276, 2024).
colon carcinoma (2 papers, 2012 to 2020). "IL18BP has previously been shown to be differentially expressed and potentially correlated with the prognosis of patients with ovarian and colon cancers." (PMID 33469515, 2020). "By using DLD1 colon carcinoma cells, we have previously shown that STAT1 binding to a gamma-activated sequence (GAS) element in the IL-18BP promoter plays a pivotal role in the regulation of IL-18BP." (PMID 22761702, 2012). "However, it has been shown that STAT3 does not affect IL-18BP expression in colon carcinoma cells." (PMID 22761702, 2012).
inflammatory skin disease (2 papers, 2012 to 2023). Inflammatory skin disorders covers a broad category that includes many conditions ranging in severity, from mild itching to grave medical health complications These disorders are common in people of all ages and races. "Currently, IL-18BP is less explored in treating inflammatory skin diseases, while IL-18BP is being tested in clinical trials for other diseases." (PMID 36742296, 2023).
liver fibrosis (2 papers, 2025 to 2026). "Sirius Red and Oil Red O staining, collagen/triglyceride/cholesterol content, as well as measurement of pro-fibrotic markers, confirmed an aggravated liver fibrosis occurring independently of any changes in liver steatosis in Il18bp−/− versus WT mice." (PMID 41275524, 2025). "After 6 weeks on CDAHFD, Il18bp−/−Ifng−/− mice exhibited similar ALT levels and steatosis as well as similar exacerbation in liver fibrosis as Il18bp−/− mice when compared with WT mice." (PMID 41275524, 2025). "Taken together, these results implicate IL-18 signaling as an important mediator of diet-induced liver fibrosis and IL-18BP as a key endogenous modulator of this process." (PMID 41275524, 2025). "Interestingly, on both diets, Il18bp-/- mice exhibited an increase in circulating transaminases levels and initiation of liver fibrosis, occurring independently of major changes in liver steatosis." (PMID 41480237, 2026).
lung carcinoma (2 papers, 2021 to 2024). "Our literature mining also supports a role for the decoy inhibitory protein, IL-18BP as being a mediator of lung cancer risk as well as IL-10, IL-12, IL-4 and TNF31." (PMID 38527997, 2024). "There were suggestive associations of increased IL-36γ with increased 17% increased lung cancer, and increased IL-18BP with a 17% decreased LUAD." (PMID 34475499, 2021).
postmenopausal osteoporosis (2 papers, 2018 to 2023). Metabolic disorder associated with fractures of the femoral neck, vertebrae, and distal forearm. "Furthermore, humanized IL-18BP has been suggested to be a treatment option for postmenopausal osteoporosis." (PMID 30081523, 2018).
prostate carcinoma (2 papers, 2023). A carcinoma that arises from epithelial cells of the prostate gland. "However, IL-18BP levels have been shown to be high in sera of patients with ovarian, non-small cell lung cancer and prostate cancer, as well as in tumor tissue of melanoma, breast, head and neck, gastric, ovarian and prostate cancers." (PMID 37298187, 2023). "The interleukin 18 binding protein (IL18BP), a potent inhibitor of IL-18, was also noted to be elevated in the urine of individuals with prostate cancer." (PMID 38250812, 2023).
viral hepatitis (2 papers, 2019 to 2025). An acute or chronic inflammation of the liver parenchyma caused by viruses. "On the basis of their analysis of this clinical case, the authors hypothesized that the IL-18BP deficiency could partially explain the fulminant viral hepatitis." (PMID 31507607, 2019). "IL-18BP (Binding Protein) is also involved and blocks IL-18 action and seems critical as a means of limiting deleterious hepatic NK responses in hepatic aggression models (see Acetaminophen-Induced ALF and Post-Viral Hepatitis A ALF)." (PMID 31507607, 2019).
acute liver failure (1 paper, 2021). Rapid deterioration of liver function causing encephalopathy and coagulopathy. "Further studies are needed to study NK cell activation, cell signaling of the JAK-STAT pathways, cytokine secretion, such as IL-18, and IL-18BP, and degranulation in NBAS deficiency especially during fever-triggered acute liver failure." (PMID 34386911, 2021).
adenomyosis (1 paper, 2022). The growth of endometrial tissue inside the muscular wall of the uterine corpus. "With CT value quantification and the 2−∆∆Ct method, significant down-regulation of IL-18BP in myometrium compared to eutopic endometrium (p < 0.05) implicates that IL-18 system acts as a local immune regulator at the level of EMI in adenomyosis." (PMID 36354688, 2022). "We uncovered that mRNA of IL-18 system, including IL-18, IL-18 receptor (IL-18R), and its antagonist, IL-18 binding protein (IL-18BP), expressed in eutopic, ectopic endometrium, and corresponding myometrium in patients with adenomyosis." (PMID 36354688, 2022).
allergic contact dermatitis (1 paper, 2023). An inflammatory skin condition caused by an immune response to direct contact between the skin and an allergen. "IL-18BP not only reduced symptoms after exposure to 2,4-dinitrofluorobenzene (DNFB) but also significantly reduced inflammation in mice with previously untreated CHS; taken together, IL-18BP is a candidate for the therapeutic indication of allergic contact dermatitis and CHS." (PMID 36742296, 2023).
anaphylaxis (1 paper, 2024). An acute hypersensitivity reaction that occurs from exposure to an allergen. "Like serum IL-18BP level may differentiate patients with urticaria from those experiencing anaphylaxis, the differences of IL-18BP in plasma might be related to differences in IL-18 neutralization, although plasma IL-18 levels did not seem to differ between the study groups (ISM and AdvSM)." (PMID 38925457, 2024).
anemia (1 paper, 2023). A reduction in the number of red blood cells, the amount of hemoglobin, and/or the volume of packed red blood cells. "Liver hepcidin 1 mRNA levels, a downstream mediator of IL-6 involved in inflammation-associated anemia, were decreased in IL-18BP KO as compared with WT mice." (PMID 37074208, 2023). "In conclusion, IL-18BP production by endothelial cells, neutrophils, macrophages, and erythroid precursors attenuates the anemia associated with murine CpG-induced MAS." (PMID 37074208, 2023). "In this study, hepcidin-1 mRNA levels were not increased, but rather significantly decreased, in IL-18BP KO compared with WT mice, further indicating that IL-6 is probably not involved in the development of anemia in CpG-induced MAS." (PMID 37074208, 2023). "Indeed, inhibition of IFN-γ signaling was not sufficient to completely rescue the severe anemia displayed by IL-18BP KO mice upon CpG injections, although the molecular signature of the IFN-γ response was drastically decreased." (PMID 37074208, 2023). "However, despite more severe anemia following CpG injections, circulating levels of IL-6 were not increased in IL-18BP KO as compared with WT mice." (PMID 37074208, 2023).
atopic asthma (1 paper, 2018). An asthma that is characterized by symptoms that are triggered by an allergic reaction caused by inhaled allergens such as dust mite allergen, pet dander, pollen and mold. "In conclusion, we found for the first time that enhanced expression of IL‐18R in monocytes, neutrophils and B cells in atopic asthma and that majority of these cell types express IL‐18BP." (PMID 28922563, 2018). "As IL‐18 can modulate IL‐18BP and IL‐18R expression, the role of IL‐18 in atopic asthma is very likely to be decided by the balance of IL‐18/IL‐18BP/IL‐18R expression in response to different allergens." (PMID 28922563, 2018). "Therefore, the aim of this study is to investigate the expression of IL‐18, IL‐18BP and IL‐18R in inflammatory cells of atopic asthma, and influence of allergens on their expression." (PMID 28922563, 2018). "As IL‐18 carries out its biological functions mainly through its receptor IL‐18R 24, and IL‐18BP is a potent endogenous neutralizing antagonist of IL‐18, it is very likely that the role of IL‐18 in atopic asthma is decided by the balance between IL‐18, IL‐18BP and IL‐18R." (PMID 28922563, 2018).
Cachexia (1 paper, 2018). Severe weight loss, wasting of muscle, loss of appetite, and general debility related to a chronic disease. "Mice treated with IL-18BP+PPI also showed a higher survival rate and lower incidence of cachexia or ascites." (PMID 29599908, 2018).
cardiomyopathy (1 paper, 2016). A disease of the heart muscle or myocardium proper. "Collectively, these studies demonstrated the protective effect of IL-18 neutralizing molecules, i.e. anti-IL-18 antibody or IL-18BP, on experimental models of cardiomyopathy." (PMID 27888626, 2016).
cholangiocarcinoma (1 paper, 2021). A carcinoma that arises from the intrahepatic biliary tree (intrahepatic cholangiocarcinoma) or from the junction, or adjacent to the junction, of the right and left hepatic ducts (hilar cholangiocarcinoma). "Finally, six AS events, SLC38A10-44114-AT, IL18BP-17488-RI, NBPF10-5531-ES, THNSL2-54469-ME, FAM3A-90629-ES, and KIAA1432-85794-AT, were identified as independent risk factors for OS in cholangiocarcinoma." (PMID 34055632, 2021).
chronic hepatitis C (1 paper, 2012). "It has been described that IFNα induces IL-18BP in chronic hepatitis C patients." (PMID 22761702, 2012).
Cognitive impairment (1 paper, 2018). Abnormal cognition is characterized by deficits in thinking, reasoning, or remembering. "Importantly, sIL-1R1, sIL-1R3, sIL-1R4, and IL-18BP negatively correlated with cognitive impairment." (PMID 30541566, 2018). "It is notable that sIL-1R1, sIL-1R3, sIL-1R4, and IL-18BP show a strong negative correlation with severity of cognitive impairment as assessed by MMSE." (PMID 30541566, 2018).
colorectal cancer (1 paper, 2024). A primary or metastatic malignant neoplasm that affects the colon or rectum. "So far, Compugen has shown that COM503 restores human tumor-infiltrating lymphocytes (TILs) and NK cell activity in human assays and that anti-mouse IL-18BP antibody is effective as a monotherapy in mouse breast cancer, colorectal cancer, and melanoma tumor models." (PMID 39769266, 2024).
diabetic nephropathy (1 paper, 2023). "IL18BP is related to inflammatory response, which plays important roles in diabetic nephropathy." (PMID 37293508, 2023).
dilatative cardiomyopathy (1 paper, 2021). "The protective effects of IL-18BP were lost in the failing heart—myocardial IL-18BP mRNA expression was significantly downregulated in both ischemic (0.25 ± 0.05, p < 0.0001) and dilatative cardiomyopathy (0.18 ± 0.02, p < 0.0001)." (PMID 34884857, 2021).
eczema (1 paper, 2017). "We therefore investigated the expression of IL-18, IL-18BP, and IL-18R on mast cells by using flow cytometry analysis and mouse eczema model." (PMID 28839348, 2017). "In conclusion, the correlation of IL-18 and IL-18BP in eczema plasma suggests an important balance between IL-18 and IL-18BP in eczema." (PMID 28839348, 2017). "IL-18 provocation increased percentage of IL-18BP+ mast cells in both inflamed and uninflamed skin areas of mouse eczema skin by 38.2% and 26.2% in comparison with that in healthy skin of mice." (PMID 28839348, 2017). "Using ELISA kits, we observed that levels of total IL-18, total IL-18BP, calculated free IL-18, and calculated free IL-18BP in the plasma of patients with eczema were elevated in comparison with HC subjects." (PMID 28839348, 2017). "Although it is not significant, eczema skin mast cells seem to produce less IL-18BP than HC skin mast cells, which supports the view that IL-18 play a role in eczema via reduced IL-18BP production in the body." (PMID 28839348, 2017). "Molar concentration ratios of IL-18BP/IL-18 were 17.3 (11.2–23.0) and 9.93 (6.9–33.7) in plasma of HC subjects and patient with eczema, respectively." (PMID 28839348, 2017). "The top 3 highest levels of total IL-18 in patients with eczema were 30.3, 35.8, and 40.0 pM, and the corresponding levels of total IL-18BP were 182.2, 185.5, and 199.6 pM, respectively." (PMID 28839348, 2017). "The aim of the current study is to investigate the correlation of IL-18 with IL-18BP in eczema, altered expression of IL-18, IL-18R, and IL-18BP in mast cells from eczema skin or cell line." (PMID 28839348, 2017). "IL-18 induced also an increase in IL-18BP+ mast cells, but a reduction of IL-18R+ mast cells in mouse eczema skin." (PMID 28839348, 2017). "Nevertheless, the ability of IL-18 in provocation of increased IL-18BP+ mast cells in both inflamed and uninflamed areas of mouse eczema skin suggests that enhanced plasma level of IL-18BP in eczema may be partially released from mast cells induced by IL-18." (PMID 28839348, 2017). "Therefore, a molar concentration ratio of free plasma IL-18BP/IL-18 appears to be a key factor to determine the role of IL-18 in eczema." (PMID 28839348, 2017). "Induction of the upregulated expression of IL-18, IL-18BP, and IL-18R on human mast cells by Der p1 and OVA suggests the possibility that allergens may cause or aggravate eczema through an IL-18-associated mechanism." (PMID 28839348, 2017). "An imbalance between IL-18 and IL-18BP may account for increased IL-18 activity in eczema." (PMID 28839348, 2017). "The decrease in molar concentration ratio of plasma IL-18BP/IL-18 and allergen-induced upregulated expression of IL-18 and IL-18R in skin mast cells of the patients with eczema suggests that anti-IL-18 including IL-18BP therapy may be useful for the treatment of eczema." (PMID 28839348, 2017). "Since the current experiment demonstrated that the molar concentration ratio of free plasma IL-18BP/IL-18 was 9.93 in the patient with eczema, it seems likely not enough IL-18BP to inhibit proinflammatory actions of IL-18 in eczema." (PMID 28839348, 2017). "However, the expression levels of IL-18, its receptor IL-18R, and its antagonist IL-18BP in mast cells of eczema have not been investigated." (PMID 28839348, 2017). "However, the plasma/serum level of IL-18BP in eczema and correlation between IL-18 and IL-18BP have not been investigated." (PMID 28839348, 2017).
endometrioid carcinoma (1 paper, 2014). ", in the endometrioid carcinoma IL-18BP was expressed in similar levels in both the epithelial cells and the stroma cells." (PMID 24963217, 2014).
enterocolitis (1 paper, 2023). An inflammatory process affecting the small intestine and colon. "However, supplementing anakinra treatment with recombinant human IL-18BP, which is a circulating decoy protein for IL-18, was able to resolve MAS parameters as well as enterocolitis in this one NLRC4V341A-expressing AIFEC patient." (PMID 38090573, 2023).
fascioliasis (1 paper, 2015). A parasitic infection that is caused by liver flukes, usually Fasciola hepatica, of sheep, goats, and cattle. "Therefore, IL18BP should be explored as a biomarker for liver damage, investigating whether it correlates with the severity of fascioliasis." (PMID 25885344, 2015).
fulminant viral hepatitis (1 paper, 2025). Fulminant viral hepatitis is a rapid and severe impairment of liver functions (acute liver failure) with hepatic encephalopathy developing less than 8 weeks after the onset of jaundice, secondary to viral hepatitis mainly due to HBV, but also to HAV. "A previous report described an inherited deficiency of IL-18BP, a soluble antagonist of IL-18, in an Algerian patient who died of fulminant viral hepatitis (FVH) A. We report here an Egyptian family with two siblings who died from FVH following infection with hepatitis A virus." (PMID 41334112, 2025).
gastric adenocarcinoma (1 paper, 2020). "The qPCR findings were consistent with our bioinformatic findings that the IL18BP expression was significantly upregulated in gastric adenocarcinoma tissues (p = 0.0072)." (PMID 33469515, 2020).
glioma (1 paper, 2024). A benign or malignant brain and spinal cord tumor that arises from glial cells (astrocytes, oligodendrocytes, ependymal cells). "Eventually, the expression of Gpnmb and Il18bp was elevated, indicating that the ‘hijacking’ of the TAM population by glioma cells was complete." (PMID 39867913, 2024).
heart failure (1 paper, 2012). Inability of the heart to pump blood at an adequate rate to meet tissue metabolic requirements. "Patients with heart failure have also been reported to show increased IL-18 but decreased IL-18BP levels." (PMID 22761702, 2012).
Hemophagocytosis (1 paper, 2010). Phagocytosis by macrophages of erythrocytes, leukocytes, platelets, and their precursors in bone marrow and other tissues. "Since IL-18 plays a major role in perpetuating hemophagocytosis, the failure of IFNγ to induce IL-18BP may constitute a fundamental pathogenetic mechanism." (PMID 20072626, 2010).